CYP4A11 (cytochrome P450 family 4 subfamily A member 11)
Description:
A cytochrome P450 monooxygenase involved in the metabolism of fatty acids and their oxygenated derivatives (oxylipins). Mechanistically, uses molecular oxygen inserting one oxygen atom into a substrate, and reducing the second into a water molecule, with two electrons provided by NADPH via cytochrome P450 reductase (CPR; NADPH-ferrihemoprotein reductase). Catalyzes predominantly the oxidation of the terminal carbon (omega-oxidation) of saturated and unsaturated fatty acids, the catalytic efficiency decreasing in the following order: dodecanoic > tetradecanoic > (9Z)-octadecenoic > (9Z,12Z)- octadecadienoic > hexadecanoic acid. Acts as a major omega-hydroxylase for dodecanoic (lauric) acid in liver. Participates in omega-hydroxylation of (5Z,8Z,11Z,14Z)-eicosatetraenoic acid (arachidonate) to 20-hydroxyeicosatetraenoic acid (20-HETE), a signaling molecule acting both as vasoconstrictive and natriuretic with overall effect on arterial blood pressure. Can also catalyze the oxidation of the penultimate carbon (omega-1 oxidation) of fatty acids with lower efficiency. May contribute to the degradation of saturated very long-chain fatty acids (VLCFAs) such as docosanoic acid, by catalyzing successive omega-oxidations to the corresponding dicarboxylic acid, thereby initiating chain shortening. Omega-hydroxylates (9R,10S)-epoxy-octadecanoate stereoisomer. Plays a minor role in omega-oxidation of long-chain 3-hydroxy fatty acids. Has little activity toward prostaglandins A1 and E1.
Synonyms: CYP4A2; CYP4AII; CP4Y; CYPIVA11
Tractability: Small molecule: it belongs to a druggable protein family. Antibody: UniProt places it where antibodies can reach, with high confidence. PROTAC: a small molecule that binds it is known.
Target class: Cytochrome P450; Cytochrome P450 family 4A; Cytochrome P450 4A11; Enzyme; Cytochrome P450 family 4
Gene: Protein-coding gene on chromosome 1 (46,928,862 to 46,941,594, reverse strand). Ensembl gene ENSG00000187048.
Subcellular location: Endoplasmic reticulum membrane; Microsome membrane
Pathways (Reactome):
Metabolism: Eicosanoids; Fatty acids; Miscellaneous substrates; PPARA activates gene expression; Synthesis of (16-20)-hydroxyeicosatetraenoic acids (HETE); Synthesis of Leukotrienes (LT) and Eoxins (EX)
Gene Ontology:
Molecular function: alkane 1-monooxygenase activity; arachidonate epoxygenase activity; arachidonate omega-hydroxylase activity; leukotriene-B4 20-monooxygenase activity; long-chain fatty acid omega-hydroxylase activity; oxidoreductase activity, acting on paired donors, with incorporation or reduction of molecular oxygen, reduced flavin or flavoprotein as one donor, and incorporation of one atom of oxygen; arachidonate monooxygenase activity; monooxygenase activity; heme binding; iron ion binding; medium-chain fatty acid omega-hydroxylase activity; oxidoreductase activity, acting on paired donors, with incorporation or reduction of molecular oxygen
Biological process: arachidonate metabolic process; epoxygenase P450 pathway; leukotriene metabolic process; long-chain fatty acid metabolic process; positive regulation of icosanoid secretion; pressure natriuresis; renal water homeostasis; sodium ion homeostasis; fatty acid metabolic process; icosanoid biosynthetic process; kidney development; lauric acid metabolic process; linoleic acid metabolic process; omega-hydroxylase P450 pathway; leukotriene B4 catabolic process; lipid metabolic process; oxylipin biosynthetic process
Cellular component: apical plasma membrane; cytoplasm; intracellular membrane-bounded organelle; endoplasmic reticulum membrane
Genetic constraint (gnomAD): Loss-of-function variants: 52 observed, 58.56 expected, observed/expected ratio (o/e) 0.89, 90% interval 0.71 to 1.12. The upper end of that interval is the gene's LOEUF score, 1.12, which puts it in group 4 of 6, group 1 being the genes least tolerant of losing a copy. Missense variants: 611 observed, 619.37 expected, observed/expected ratio (o/e) 0.99, 90% interval 0.92 to 1.05. Synonymous variants: 216 observed, 238.87 expected, observed/expected ratio (o/e) 0.9, 90% interval 0.81 to 1.01.
Homologues: Orthologues: macaque CYP4A45 (94% identical), macaque CYP4A11 (93% identical), mouse Cyp4a10 (76% identical), rat Cyp4a1 (76% identical), mouse Cyp4a32 (75% identical), mouse Cyp4a31 (74% identical), rat Cyp4a3 (71% identical), mouse Cyp4a30b (68% identical), chimpanzee CYP4A22 (59% identical), tropical clawed frog cyp4b1.5 (54% identical), tropical clawed frog XB5810926 (54% identical), tropical clawed frog cyp4b1.2 (54% identical), and 30 more. Paralogues in human: CYP4A22 (95% identical), CYP4B1 (52% identical), CYP4Z1 (50% identical), CYP4X1 (47% identical), CYP4F3 (45% identical), CYP4F2 (45% identical), CYP4F11 (45% identical), CYP4F8 (44% identical), CYP4F12 (44% identical), CYP4F22 (42% identical), CYP4V2 (32% identical), CYP19A1 (20% identical).
Diseases named in the same sentence as CYP4A11 in open-access papers:
CYP4A11 is named in the same sentence as 42 diseases in open-access papers, as found by Europe PMC text mining. Sharing a sentence is not in itself a finding about the gene and the disease. The quoted sentences say what the papers report.
Hypertension (17 papers, 2012 to 2025). The presence of chronic increased pressure in the systemic arterial system. "CYP4A11 is a highly polymorphic gene with overexpression in humans that increases 20-HETE serum levels associated with hypertension and plaque in patients with ischemic stroke." (PMID 40452921, 2024). "The result reveals that CYP4A11 T8590C polymorphism can increase the risk of hypertension in all models." (PMID 32373936, 2020). "In summary, our meta-analysis proved that rs1126742 polymorphism of the CYP4A11 gene significantly increases the risk of hypertension." (PMID 32373936, 2020). "A meta-analysis has shown that RGS2 1891-1892del TC polymorphism and CYP4A11 T8590C polymorphism were associated with hypertension risk." (PMID 31906879, 2020). "Significant associations were found between CYP4A11 gene T8590C polymorphism and hypertension under all genetic models (allele, homozygote, heterozygote, recessive, and dominant model)." (PMID 32373936, 2020). "The current meta-analysis concluded that the rs1126742 polymorphism of CYP4A11 significantly increases the risk of hypertension, particularly in Caucasian." (PMID 32373936, 2020). "Variants in CYP4F2 and CYP4A11 have been repeatedly linked to hypertension, stroke, and cardiovascular disease." (PMID 31514409, 2019). "Emerging evidence demonstrates that several SNPs in CYP4F2 and CYP4A11 are associated with hypertension and stroke in several populations." (PMID 31514409, 2019). "The SNPs of rs1126742 (F434S), rs9333025, and rs389011 in CYP4A11 were found to be associated with hypertension and stroke in American, Chinese, and Japanese populations." (PMID 31514409, 2019). "Many of these studies have discovered an association between some of these SNPs and the susceptibility to hypertension and coronary artery disease, making CYP4A11 and CYP4F2 reasonable candidate genes for altering the risk of CVD." (PMID 29484037, 2018). "Of the eleven excluded studies, one paper was a repeat publication, four were reviews and four were unrelated to the CYP4A11 T8590C polymorphism and hypertension." (PMID 24278241, 2013). "Both animal and human studies indicate that the CYP4A11 gene is a candidate causative gene for hypertension." (PMID 24278241, 2013). "In summary, our meta-analysis suggests that the CYP4A11 T8590C polymorphism is associated with risk of hypertension in the general population, especially in Caucasians." (PMID 24278241, 2013). "The results concerning the role of CYP4A11 polymorphisms in susceptibility to hypertension were conflicting." (PMID 24278241, 2013). "Recent studies have attempted to clarify the potential association between CYP4A11 and essential hypertension." (PMID 24278241, 2013). "In humans, previous studies have shown that the CYP4A11 T8590C polymorphism appears to be a useful genetic marker of essential hypertension in men." (PMID 24278241, 2013). "Given this background, the aim of this study was to investigate the possible association between the CYP4A11 T8590C variant and essential hypertension in the Chinese Han population." (PMID 24278241, 2013). "The funnel plot and Egger’s test suggested that the selection of publications was an unlikely source of bias in this meta-analysis of the association between the CYP4A11 T8590C polymorphism and essential hypertension." (PMID 24278241, 2013). "As genotyping costs fall, clinically validated variants, particularly those in NOS3, MMPs, and CYP4A11, may contribute to personalized hypertension management, guiding early screening and pharmacogenetic interventions." (PMID 41573461, 2025). "We may conclude that 20-HETE affected the formation of hypertension and single-nucleotide polymorphisms (SNPs) of CYP4A11 can explain susceptibility of hypertension." (PMID 32373936, 2020). "And CYP4A11 gene rs1126742 variants may also have a role in hypertension with a gender-specific effect." (PMID 32373936, 2020).
Hypertension (continued). "SNP T8590C (rs1126742) is the most extensively investigated polymorphism in the CYP4A11 gene that has been shown to be associated with the level of blood pressure and hypertension susceptibility as well as with endothelial dysfunction in the coronary arteries in patients with CAD in Europeans." (PMID 29484037, 2018). "At least, this suggestion may be supported by the study in Japanese population that reported a relationship between the SNP rs9332978, expression of CYP4A11, and the hypertension risk." (PMID 29484037, 2018). "In addition, a meta-analysis was conducted, including studies examining the association between the CYP4A11 T8590C variant and the risk of hypertension, to clarify previous inconsistencies." (PMID 24278241, 2013). "Allelic variations in CYP4A11 are suggested to result in an increased risk for hypertension." (PMID 23359794, 2013). "Further large-scale studies are needed to clarify whether the CYP4A11 T8590C polymorphism is associated with hypertension risk in Asians or has a gender-specific effect." (PMID 24278241, 2013). "Therefore, it may be concluded that there is an association between the CYP4A11 T8590C polymorphism and hypertension risk in the general population, especially among Caucasians." (PMID 24278241, 2013). "Several variants, including PRKG1 rs1904694, CYP4A11 rs1126742, and CYBA rs4673, demonstrated associations with increased hypertension susceptibility." (PMID 41573461, 2025). "This review summarizes recent genetic variants in CYP4F2, and CYP4A11 influencing 20-HETE production and discusses the role of 20-HETE in hypertension and the susceptibility to the onset, progression, and prognosis of ischemic and hemorrhagic strokes." (PMID 31514409, 2019). "Given the role of 20-HETE in the regulation of hypertension, CYP4A11 is the subject of much research interest." (PMID 24278241, 2013). "Other SNPs affecting cholesterol levels (EDN1 K198N; OMIM_ID # 131240), familial obesity (FAM71F1 E143K; rs6971091) and hypertension susceptibility (PPARFC1A, G482S; rs8192678 and CYP4A11, F434S; rs1126742) were also found in the genome." (PMID 22938532, 2012). "Furthermore, 20-hydroxyeicosatetraenoic acid (20-HETE) has renoprotective actions in hypertension, and mutations in CYP4A11 that produces 20-HETE have been linked to elevated blood pressure in humans, indicating the important role of CYP4A11 in HTN." (PMID 27756246, 2016). "Notably, human mutations in CYP450 hydroxylase enzymes, particularly CYP4A11 and CYP4F2, are linked with increased prevalence of ischemic stroke and hypertension, especially in males, while certain single nucleotide polymorphisms in CYP4F2 are associated with decreased 20-HETE production." (PMID 34819839, 2021). "Four SNPs (PRKG1/rs1904694 and rs7897633, CYP4A11/rs1126742, and CYBA/rs4673) were still significantly associated after Bonferroni correction (P < 0.0007) adjusted for age, sex, fasting blood glucose, total cholesterol, salt-eating habit, physical activity, and hypertension." (PMID 34671380, 2021). "Moreover, renal cadmium reduces CYP4A11 and PPARs, which may be related to hypertension and sodium retention." (PMID 23762083, 2013). "The opposing roles of CYP2E1 19-HETE and CYP4A11 20-HETE are apparent from 19-HETE’s antagonism of 20-HETE-induced vascular sensitization and hypertension, inhibition of the Na+/K+-ATPase and functions to increase volume absorption in renal proximal tubules." (PMID 40452921, 2024). "Although more research is necessary to confirm the relevance of CYP to sodium-induced hypertension in humans, our results corroborate human research showing that CYP2J2 and CYP4A11 are related to hypertension." (PMID 31065462, 2019). "CYP4A11 is mainly used as an enzyme to convert arachidonic acid (AA) into 20-hydroxytetradecanoic acid (20-HETE) and 20-HETE plays a pivotal role in the regulation of hypertension." (PMID 32373936, 2020).
Hypertension (continued). "Furthermore, the alcohol-induced decrease in CYP4A11 abundance, which is involved in the synthesis of eicosanoids, may affect the 20-HETE signaling pathways and contribute to mechanisms of alcohol-induced hypertension." (PMID 39997363, 2025).
hepatocellular carcinoma (4 papers, 2010 to 2024). A malignant tumor that arises from hepatocytes. "A high-fat diet induces the ω-oxidation of fatty acids and increases the expression of CYP4A11 in HepG2 human hepatoma cells." (PMID 40452921, 2024). "However, CYP4A11 was downregulated in hepatocellular carcinoma 11, although the liver and kidney showed the highest levels of CYP4A11 mRNA expression." (PMID 32047554, 2020). "For example, ARG1, CYP2C8, CYP3A4, CYP3A7 and CYP4A11, which we identified using MOG as decreasing expression with LIHC progression, have each been recently studied as prognostic markers for hepatocellular carcinoma." (PMID 31956905, 2020). "The mRNA abundance of PPARα-target genes that control fatty acid oxidation, such as CYP4A11, ACOX, and UCP1 significantly increases in human hepatoma cells." (PMID 20811644, 2010).
Cirrhosis (3 papers, 2021 to 2024). A chronic disorder of the liver in which liver tissue becomes scarred and is partially replaced by regenerative nodules and fibrotic tissue resulting in loss of liver function. "CYP4A11 protein levels increased in steatosis and steatohepatitis but dramatically decreased in cirrhosis and then increased in HCC." (PMID 39959811, 2024). "The increase in P4504A11 protein levels in steatosis, steatohepatitis, and HCC cirrhosis is consistent with the altered patterns of CYP4A11 mRNA results." (PMID 39959811, 2024). "The dramatic decline in CYP4A11 mRNA and protein in cirrhosis has been confirmed with multiple CYP4A11 primer sets and two different P4504A11 peptide-specific antibodies compared to β-actin used as a loading control." (PMID 39959811, 2024). "Many issues need to be addressed before determining the roles of the CYP4A11-mediated 20-HETE and CYP2E1-related 19-HETE in steatosis, steatohepatitis, cirrhosis, and HCC, and possible therapeutic targets in the treatment of CLD." (PMID 40452921, 2024). "We found that both CYP4A11 and CYP4A22 were highly expressed specifically in hepatocytes compared with nonhepatic parenchymal cells, and that levels increased in patients with cirrhosis compared with healthy controls." (PMID 34423788, 2021). "We also explored CYP4A11 and CYP4A22 expression in the liver of patients with cirrhosis using a recently published and publicly available data set." (PMID 34423788, 2021). "The abrupt reduction in CYP4A11 and GPR75 in patients with cirrhosis may also be due to increased 20-HETE, serving as a feedback mechanism via GPR75, leading to reduced CYP4A11 and GPR75 gene expression." (PMID 39959811, 2024). "In liver samples of cirrhosis, CYP4A22 increases while CYP4A11 and CYP4F2 decrease." (PMID 39959811, 2024). "Interestingly, the CYP4A11 and GPR75 mRNA levels increased in steatohepatitis but dramatically dropped in cirrhosis and then increased in patients with HCC." (PMID 39959811, 2024). "We also detail the role of the CYP4A11 and CYP2E1 arachidonic metabolites and their possible functional role in portal hypertension in hepatic cirrhosis and suggest alteration in these pathways may be therapeutic targets in the treatment of chronic liver disease." (PMID 40452921, 2024).
coronary artery disease (2 papers, 2018 to 2023). "There is growing evidence suggesting that CYP enzymes play a pivotal role in the cardiovascular system; for example, polymorphisms in CYP4A11 have associations with coronary artery diseases." (PMID 38003044, 2023). "This is the first study in Europeans that reported association between polymorphism rs9332978 of CYP4A11 and susceptibility to coronary artery disease." (PMID 29484037, 2018). "Further pharmacogenomic studies are needed to substantiate the contribution of CYP4A11 polymorphisms in the pathogenesis of coronary artery disease and to assess the dual role of 20-hydroxyeicosatetraenoic acids in cardiovascular homeostasis as a promising target for vascular medicine in the future." (PMID 29484037, 2018). "Moreover, our study provided additional evidence that CYP4A11 is an important susceptibility gene for coronary artery disease despite the fact that different polymorphisms of the gene showed association with disease risk in various populations." (PMID 29484037, 2018). "The present study identified that polymorphism rs9332978 of CYP4A11 could be a novel marker of genetic susceptibility to coronary artery disease, at least in Europeans." (PMID 29484037, 2018). "Altogether, these data make SNP rs9332978 of CYP4A11 a subject of great interest for further research of molecular pathogenesis of coronary artery disease." (PMID 29484037, 2018). "The purpose of this study was to investigate whether common single nucleotide polymorphisms in the CYP4A11 and CYP4F2 genes are associated with susceptibility to coronary artery disease in Russian population." (PMID 29484037, 2018). "Enzymes CYP4A11 and CYP4F2 are involved in biosynthesis of vasoactive 20-hydroxyeicosatetraenoic acid and may contribute to pathogenesis of coronary artery disease (CAD)." (PMID 29484037, 2018).
diabetes (2 papers, 2018 to 2024). "Cyp4a32 and its human ortholog CYP4A11 are part of the Cyp4a gene family encoding cytochrome 450 liver enzymes that can ω-hydroxylate fatty acids and which are induced by starvation and diabetes." (PMID 30091978, 2018). "The synergistic role of CYP2E1 and CYP4A11 in the saturated and unsaturated fatty acids metabolism indicates their vital role in fasting, diabetes, and the progression of MASLD." (PMID 40452921, 2024).
ischemic stroke (2 papers, 2019 to 2021). A stroke disorder caused by obstruction of blood flow to the brain, due to thrombotic (local blood clot formation) or embolic (due to a blood clot or other material traveling from another site) event. "Ischemic stroke patients who have both rs9333025 GG (CYP4A11) and rs2108622 GG (CYP4F2) variants have higher plasma 20-HETE levels." (PMID 31514409, 2019). "In contrast, ischemic stroke patients with both CYP4A11 (rs9333025) and CYP4F2 (rs2108622) SNPs exhibit elevated plasma 20-HETE levels." (PMID 31514409, 2019).
liver disease (2 papers, 2009 to 2024). "In humans with obesity, CYP4A11 mRNA decreased by 50% while in NAFLD patients while CYP4A11 mRNA increases 4-fold, suggesting a differential regulation in liver disease progression." (PMID 20300478, 2009).